GHSR (growth hormone secretagogue receptor)
Diseases named in the same sentence as GHSR in open-access papers (continued):
Sharing a sentence is not in itself a finding about the gene and the disease.
Anxiety (continued). "Since GHSR expression is extensive in the corticotropic cells in the anterior pituitary, it is likely that reduced activation of pituitary GHSR in ghr-/- mice is responsible for reduced ACTH levels, diminished negative feedback on the HPA axis and increased anxiety in these animals." (PMID 28282447, 2017).
Anorexia (21 papers, 2010 to 2026). Lack of desire to eat (loss of appetite). "Although ghrelin and synthetic GHSR-1a agonists have been investigated for the treatment of anorexia, sarcopenia and cancer cachexia, their clinical utility has been limited by unfavourable pharmacokinetics." (PMID 41923173, 2026). "The 28-amino acid peptide hormone ghrelin and its receptor, the growth hormone secretagogue receptor (GHSR), play a crucial role in regulating appetite and are therefore relevant for cancer-associated anorexia and cachexia." (PMID 38753262, 2024). "Anamorelin is a ghrelin receptor agonist that stimulates the growth hormone secretagogue receptor (GHSR), that has been developed for treating anorexia and weight loss." (PMID 38140041, 2023). "RKT was reported to increase GHSR expression in the hypothalamus in a cisplatin-induced anorexia model." (PMID 32024850, 2020). "In summary, ghrelin prevents LLC tumor-induced body weight and fat loss by a combination of GHSR-1a-dependent mechanisms including preventing anorexia, and other mechanisms that are partly GHSR-1a-independent such as WAT lipolysis." (PMID 32934774, 2020). "Atractylodin is one of the main constituents in the rhizomes of Atractylodes lancea Thunb., being capable of treating cancer cachexia-anorexia and age-related diseases as an agonist of growth hormone secretagogue receptor (GHSR)." (PMID 28883883, 2017).
depression (19 papers, 2010 to 2024). "A genome-wide DNA methylation profile analysis conducted on 34 monozygotic twins with depressive symptoms showed that GHSR DNA methylation was highly associated with depression." (PMID 33664648, 2021). "Associative studies that examine a ghrelin-mood relationship also exist, including one in which a GHSR polymorphism was found associated with major depressive disorder and another in which total plasma ghrelin levels were compared among subjects with major depression, schizophrenia, and controls." (PMID 20721341, 2010). "Deleting neuronal GHSR improves depression and cognitive function and attenuates neuroinflammation in the context and hippocampus, and we believe that neuroinflammation is one of the driving forces of these behavioral phenotypes." (PMID 38464534, 2024). "In terms of regulating mood, GHSR signaling reduces anxiety and depression-like symptoms in a model of chronic social defeat and a Leu72Met gene polymorphism in the human ghrelin gene associates with major depression." (PMID 31998738, 2019). "Thus, the ghrelin/GHSR system has many potent functions in the defense against depression-like symptoms." (PMID 39057075, 2024). "Numerous studies have suggested that the ghrelin/GHSR system may be involved in the pathophysiologic process of depression." (PMID 39057075, 2024). "In conclusion, there are many unknown connections between the monoamine system and the ghrelin/GHSR system, and more research is needed to determine whether monoamine receptors can be used as targets in the treatment of depression." (PMID 39057075, 2024). "Thus, there is increasing evidence of the mediating role of the ghrelin/GHSR system in regulating pro-inflammatory cytokine release events in depressive disorders." (PMID 39057075, 2024). "Moreover, ghrelin and the growth hormone secretagogue receptor can defend animals against stress-induced depression-like symptoms." (PMID 33117967, 2020). "This suggests that the effects of caloric restriction on depression-like behaviors may depend on GHSR signaling in the hippocampus and ensuing neurogenesis." (PMID 33192444, 2020). "Therefore, the ghrelin/GHSR system is becoming a new target for the treatment of depression." (PMID 39057075, 2024). "Furthermore, ghrelin/GHSR can activate multiple signaling pathways, including cAMP/CREB/BDNF, PI3K/Akt, Jak2/STAT3, and p38-MAPK, to produce antidepressant effects, given which it is expected to become a potential therapeutic target for the treatment of depression." (PMID 39057075, 2024). "In such cases, not only do these treatments amplify neurotransmitter receptor signaling, but they may have other possible effects such as reduction in depression, neuroprotection, and stimulation of appetite—all effects that may relate to the effects on GHSR alone and not the dimer." (PMID 26464979, 2015).
prostate carcinoma (15 papers, 2013 to 2025). A carcinoma that arises from epithelial cells of the prostate gland. "GHSR genes are also previously reported to associate with prostate cancer risk." (PMID 28765617, 2017). "For the characterization of this antibody we used a line of human prostate cancer, described as positive for GHSR, in immunoprecipitation and flow cytometry experiments." (PMID 23755116, 2013). "Human prostate carcinomas and benign neoplasms express ghrelin and GHSR mRNA." (PMID 38137497, 2023). "Ghrelin may also influence cell migration and invasion capacity and consequently metastasis in several types of cancer by the GHSR/PI3K/Akt signaling pathway; in contrast, its role in breast and prostate cancers is controversial." (PMID 35008278, 2021).
breast carcinoma (12 papers, 2007 to 2023). "The increased risk associated with the GHSR SNP rs572169 in breast and colorectal cancer (OR 1.42-1.43, p = 0.08) was also increased only when breast cancer was considered (OR 1.69-1.70, p = 0.14)." (PMID 25376984, 2014). "The GHRL rs2075356 (3056 T > C) and GHSR rs572169 (Gly57Gly) SNPs were found to be associated with 20% increased risk of breast cancer in a European study with 1,324 cases and 2,360 controls." (PMID 25376984, 2014). "In contrast, the rs4684677 GHRL and the rs572169 GHSR polymorphisms conferred increased breast cancer risk (OR 1.97-1.98, p = 0.08 and OR 1.42-1.43, p = 0.08, respectively)." (PMID 25376984, 2014). "A meta-analysis of case–control studies showed that the rs4684677 polymorphism in the GHRL gene and the rs572169 polymorphism in the GHSR gene confer an increased risk of breast cancer, whereas the rs696217 and rs2075356 polymorphisms in the GHRL gene protect carriers against breast cancer." (PMID 38137497, 2023). "However, another nested case-control (1,359 cases/2,389 controls) reported associations of some polymorphisms (GHRL rs171407-G allele and GHSR 2948694-GG genotype) with increased risk of breast cancer." (PMID 31681567, 2019). "Genes MIR124-2, PBX1, SKI, GHSR and RBPMS were reported to be associated with breast cancer, and a gene CYP19A1 was reported to be be associated with endometrial cancer." (PMID 31640538, 2019). "Growth hormone secretagogue receptor expression was significantly higher in the cell lines isolated from mammary carcinoma metastases to the lungs (see also our previous paper:)." (PMID 22999388, 2012). "Finally, associations of Gly57Gly SNP of GHSR with increased risk, and association of some rare haplotypes of GHRL with reduced risk of breast cancer were reported." (PMID 31681567, 2019). "This study suggests that the rs696217 and rs2075356 ghrelin gene (GHRL) polymorphisms may protect carriers against breast cancer, and the rs4684677 GHRL and rs572169 GHSR polymorphisms may increase the risk among carriers." (PMID 25376984, 2014). "In summary, our results indicate that GHRL and GHSR SNPs may be involved in the pathophysiology of breast cancer." (PMID 25376984, 2014). "Furthermore, since GHSR 1b is reported to be an inactive isoform of the receptor, loss of expression of GHSR 1a and overexpression of GHSR 1b may be functionally equivalent mechanisms of altering the ghrelin/GHSR axis in breast cancer." (PMID 18091988, 2007). "Immunohistochemistry also demonstrated expression of growth hormone secretagogue receptor (GHS-R) in all benign and malignant canine mammary tumors." (PMID 22999388, 2012). "Increased risks were also observed in the co-dominant model of breast cancer studies for the rs4684677 GHRL SNP (OR 1.11, p = 0.23) and the GHSR rs572169 SNP, both overall and in breast cancer (OR 1.08-1.10), with borderline significance (p = 0.05), all homogeneously obtained (I2 = 0-46%)." (PMID 25376984, 2014).
diabetes (12 papers, 2008 to 2025). "Aging increases vulnerability to diabetes, so we studied β-cell-GHSR-deficient mice under STZ-induced hyperglycemia." (PMID 38794702, 2024). "Overall, our findings suggest that β-cell GHSR plays a crucial role in β-cell function and the development of diabetes in aging." (PMID 38794702, 2024). "Our study found that the levels of Ghrelin and GHSR mRNA in diabetes rats decreased significantly, while after 4 weeks administration, Yunvjian promoted Ghrelin and GHSR mRNA level." (PMID 36691597, 2023). "In this study, GHSR-1a was detected in HRMECs, and the expression of GHSR-1a in HRMECs under high-glucose conditions was significantly lower compared with the control group, indicating that the downregulation of ghrelin-GHSR-1a signaling may be related to retinal vascular injury in diabetes." (PMID 35668539, 2022).
sarcopenia (11 papers, 2016 to 2026). Progressive decline in muscle mass due to aging which results in decreased functional capacity of muscles. "We examined the effects of GHSR-1a deletion on sarcopenia measurements (muscle mass, strength, and endurance) by comparing young and aged male GHSR-1a knockout (KO) and wildtype (WT) mice (6-, 24-, and 28-month-old)." (PMID 41986945, 2026).
type 2 diabetes (11 papers, 2008 to 2026). "According to our results, the application of other metabolic disorder-associated experimental models (e.g., type 1 diabetes and type 2 diabetes) may further advance the relationship between the nesfatin-1 and GHSR." (PMID 30405536, 2018). "Thus, elevated ghrelin-GHSR activity could be causally implicated in type 2 diabetes." (PMID 26370322, 2015). "The novel β-cell specific GHSR-cAMP/TRPM2 signaling provides a potential therapeutic target for the treatment of type 2 diabetes." (PMID 26370322, 2015). "Studies of associations between GHSR -151 promoter variant and quantitative traits in 15,854 Danes without known type 2 diabetes." (PMID 20404923, 2010). "None of the GHSR polymorphisms were statistically significantly associated with risk of type 2 diabetes (data not shown)." (PMID 18698404, 2008). "Hence, developing methods to specifically intervene the GHSR-cAMP/TRPM2 cascade in β-cells may provide a potential therapeutic tool to treat patients with type 2 diabetes." (PMID 26370322, 2015).
Hyperglycemia (9 papers, 2013 to 2025). An increased concentration of glucose in the blood. "All three CHM formulas not only affect ACE but also blood sugar control related target proteins such as DPP4 and GHSR, meaning that they can help reduce the risk of precipitating hyperglycemia caused by COVID-19 as well as lower the blood sugar level of pre-existing DM." (PMID 35890093, 2022). "Of interest, despite the induction of hyperglycemia in both genotypes, the mean blood glucose attained in ghrelin-KO mice was lower than that observed in WT mice, similar to previously-reported effects of STZ in GHSR-null mice." (PMID 33042003, 2020).
colitis (8 papers, 2015 to 2025). Inflammation of the colon. "GHSR contributes to development of acute DSS-induced colitis, likely via elevated pro-inflammatory cytokines and activation of macrophages." (PMID 25825652, 2015). "The temporal expression of GHSR/ghrelin was determined in dextran sulphate sodium (DSS) induced colitis in Wt mice." (PMID 25825652, 2015). "Our data demonstrated that GHSR contributes to the development of DSS-induced colitis, and suggest GHSR as a potential therapeutic target for IBD." (PMID 25825652, 2015). "In the current work, we demonstrated that GHSR regulated the development of acute DSS-induced colitis in vivo and participated in macrophages activation in vitro." (PMID 25825652, 2015). "Recently, ghrelin is also involved in experimental colitis, but the role of GHSR in the development of colitis is unclear." (PMID 25825652, 2015). "The severity of DSS induced colitis from GHSR−/− and WT mice was compared at clinical/pathological levels." (PMID 25825652, 2015). "Considering the close biological linkage between ghrelin and GHSR, it is reasonable to hypothesise that GHSR contributes to the pathogenesis of colitis." (PMID 25825652, 2015). "DSS-induced colitis was ameliorated in GHSR−/− mice compared to WT." (PMID 25825652, 2015). "In the current study, the expression of GHSR in colon and MLN was upregulated following the progression of DSS-induced colitis, suggesting GHSR contributes to inflammatory response in colon." (PMID 25825652, 2015). "DSS-induced colitis was used to explore the pathogenesis of GHSR in colitis, the severity of disease was determined at both clinical and pathological levels from GHSR knockout (GHSR−/−) mice and their WT littermates." (PMID 25825652, 2015). "Our results demonstrated amelioration of colon shortening in GHSR−/− mice compared to WT mice following 7 days of DSS challenge, suggesting GHSR plays a key role in the development of acute colitis." (PMID 25825652, 2015). "Similar pro-inflammatory involvement of GHSR-1a was observed in experimental colitis, where the lack of GHSR significantly attenuated colitis at both clinical and pathological levels, reducing colonic pro-inflammatory cytokines." (PMID 40137085, 2025). "Lack of GHSR attenuated colitis significantly at the clinical and pathological levels with reduced colonic pro-inflammatory cytokines (P < 0.05)." (PMID 25825652, 2015). "The role of GHSR was further determined in DSS-induced colitis from GHSR−/− mice and their WT littermates, showing that lack of GHSR significantly ameliorated the severity of acute DSS-induced colitis at clinical, macroscopic and microscopic levels, compared to WT mice." (PMID 25825652, 2015).
colorectal cancer (8 papers, 2010 to 2024). A primary or metastatic malignant neoplasm that affects the colon or rectum. "We conducted a case-control study to examine the association of common genetic variants in the genes coding for ghrelin (GHRL) and its receptor (GHSR) with colorectal cancer risk." (PMID 20920174, 2010). "We examined the relative expression levels of ghrelin‐GHSR system in colorectal cancer cell lines Caco‐2 and SW480, along with NCM460, a non‐malignant colon epithelial cell line." (PMID 27464938, 2016). "The differential expression of ghrelin and GHSR1a was indicative the fact that ghrelin‐GHSR axis might be involved in malignant behavior of colorectal carcinoma through autcorine/paracrine means." (PMID 27464938, 2016). "In addition, we also provided further evidence for this hypothesis, which was that the ghrelin‐GHSR axis is significantly upregulated in human well‐differentiated and moderately differentiated colorectal cancer tissue samples in contrast to normal colorectal tissues." (PMID 27464938, 2016). "However, it remains unknown whether GHSR contributes to colorectal cancer proliferation." (PMID 27464938, 2016). "The absence of correlation between the levels of ghrelin or GHSR1a and tumor grades was suggestive the phenomenon that ghrelin‐GHSR axis apparently operates in low‐grade colorectal cancer, but does not functions in high‐grade colorectal cancer." (PMID 27464938, 2016).
heart failure (7 papers, 2014 to 2025). Inability of the heart to pump blood at an adequate rate to meet tissue metabolic requirements. "However, we have shown similar patterns of correlation between GHSR and heart function in two studies utilizing human tissue and in a recent study in a canine model of heart failure." (PMID 40643523, 2025). "Our results demonstrate an elevation in GHSR in the myocardium of the mdx:utrn−/− mice at end-stage cardiomyopathy, which is in agreement with the elevated levels of GHSR reported in end-stage human heart failure." (PMID 40643523, 2025). "Indeed, both GHSR and sST2 are involved in hypertrophic response related to the stretch of cardiomyocytes, and they are both considered a marker of heart failure since they increase with the severity of ventricular dysfunction in human disease." (PMID 36768322, 2023). "Furthermore, GHSR-1a expression was observed to be increased in heart failure after myocardial infarction (MI) in rats." (PMID 25120643, 2014).
Hypoglycemia (7 papers, 2012 to 2023). A decreased concentration of glucose in the blood. "In addition, continuous LEAP2 treatment of calorie-restricted GHSR-knockout mice could still induce body weight loss, hypoglycemia, and body temperature reduction, implying LEAP2’s ghrelin–GHSR signaling independent effects." (PMID 36387867, 2022). "Although glucose levels were identical in ad libitum-fed wild-type, GHSR-null and GHSR-null/Phox2b mice, following a fast, GHSR-null mice exhibited significant hypoglycemia compared to wild-type mice, as expected." (PMID 22952883, 2012). "Hypoglycemia is also observed in GHSR-null mice following the same prolonged caloric restriction protocol and upon initiation of acute caloric restriction of both ghrelin ko and GHSR ko mice, although both genotypes adapted after 14 days." (PMID 26042199, 2015). "Using a unique set of four different genetic loss-of-function models for the GOAT/ghrelin/growth hormone secretagogue receptor (GHSR) system, we thoroughly tested the hypothesis that lack-of-ghrelin activation or signaling would lead to hypoglycemia during caloric deprivation." (PMID 22363801, 2012). "Selective GHSR expression in ARC AgRP neurons is sufficient to allow ghrelin to induce food intake and normalizes the relative hypoglycemia observed in fasted GHSR-null mice." (PMID 37962950, 2023). "In contrast, we found that calorie restriction does not induce hypoglycemia in 9-month-old mice with ghrelin, GOAT or GHSR deficiency, suggesting that a potential prevention from hypoglycemia may be age-dependent." (PMID 23630616, 2013). "Notably, selective GHSR expression in the hindbrain was sufficient to normalize this relative hypoglycemia, as fasting glucose levels in the GHSR-null/Phox2b mice were significantly different from those in GHSR-null mice n = 25) p<0.05) and not significantly different from those in wild-type mice." (PMID 22952883, 2012).
malnutrition (7 papers, 2012 to 2023). Inadequate nutrition resulting from poor diet, malabsorption, or abnormal nutrient distribution. "Ghrelin and GHSR have been used as the targets for treating many diseases such as cancer anorexia-cachexia, functional gastrointestinal disorders, and malnutrition, even prolonging the survival of patients with age-related syndromes." (PMID 28883883, 2017). "Finally, a selective agonist of the ghrelin/growth hormone secretagogue receptor, anamorelin (ONO-7643), may be interesting in fighting preoperative malnutrition." (PMID 36980767, 2023).
non-small cell lung carcinoma (7 papers, 2017 to 2025). A group of at least three distinct histological types of lung cancer, including non-small cell squamous cell carcinoma, adenocarcinoma, and large cell carcinoma. "Finally, GHSR antagonist attenuated cell proliferation associated with MAPK/ERK and PI3K/AKT signaling in Gefitinib-resistant non-small cell lung cancer cell lines." (PMID 31681567, 2019). "Furthermore, GHSR expression was linked to the activation of the MAPK/ERK and PI3K/AKT signaling and accompanied cell proliferation in Gefitinib (epidermal growth factor tyrosine kinase inhibitor)-resistant non-small cell lung cancer cell lines." (PMID 31681567, 2019).